TLR9 (toll like receptor 9)
Diseases named in the same sentence as TLR9 in open-access papers (continued):
Sharing a sentence is not in itself a finding about the gene and the disease.
autoimmune disease (continued). "Similar expression of TLR9 in CD4+ T cells and B cells indicate that even CD4+ T cells could play a role by involving TLR9 under autoinflammatory and autoimmune disease conditions." (PMID 37406035, 2022). "Although both TLR7 and TLR9 are involved in autoantibody production to nuclear self-antigens, TLR7 but not TLR9 is required for the development of autoimmune disease in a mouse model." (PMID 28408984, 2017). "SRMA itself seems to be maintained by multiple alterations of the immune system resulting in an autoimmune disease, TLRs, such as TLR4 and TLR9, might act as receptors maintaining the inflammation." (PMID 23016675, 2012). "The fact that some of the TLRs have a tolerogenic function, such as TLR9, which may be responsible for the establishment of central B-cell tolerance, makes it an important target to restore B-cell tolerance in SLE and other autoimmune diseases." (PMID 38791389, 2024). "TLR-7/8 and TLR-9 agonists are used in mRNA/DNA SARS-CoV-2 vaccinations as “adjuvants,” which may encourage the subset of ABC to produce autoantibodies and post-vaccination autoimmune disorders." (PMID 37896974, 2023). "Moreover, concomitant stimulation of ß1-3-ADRs together with a B cell receptor (BCR)/TLR9 stimulus clearly enhances the anti-inflammatory potential of Bregs to suppress CD4 T cells, a crucial population in the pathogenesis of autoimmune diseases, like rheumatoid arthritis (RA)." (PMID 35073310, 2022). "In the absence of TLR9, autoimmune disease is exacerbated, resulting in heightened activation of lymphocytes and plasmacytoid DC, as well as elevated levels of serum IgG and IFN-α, suggesting the activation of TLR9 may be potential therapeutic strategies for SLE." (PMID 37667233, 2023). "We hypothesize that this difference in TLR9 recruitment between SLE and healthy pDCs may partly contribute to the lack of induction of Treg cells development in SLE, and this may further contribute to the tolerance break-down and autoimmune disease development." (PMID 20618924, 2010).
melanoma (87 papers, 2009 to 2025). A malignant, usually aggressive tumor composed of atypical, neoplastic melanocytes. "Some studies have reported that Ltf deficiency in mice promotes metastasis of melanoma cells to the lung by downregulating the TLR9 signaling pathway to recruit bone marrow-derived suppressor cells." (PMID 35806481, 2022). "Additionally, in an independent cohort of patients with high-risk resectable melanoma treated with anti–PD-1 and a TLR9 agonist, high sucralose intake was associated with a significantly lower probability of MPR and lower RFS (median 25.0 vs. 19.0 months, log-rank P = 0.012)." (PMID 40742298, 2025). "Indeed, the combination of a TLR9 agonist (SD-101) with the anti-PD-L1 monoclonal antibody, pembrolizumab is associated with a better infiltration of DCs in the tumor and promising clinical results in melanoma." (PMID 37190135, 2023). "Thirteen studies, mainly phase I/II trials in melanoma, rectal, and other solid tumors, evaluated vidutolimod (a Toll-like receptor 9 agonist) combined with nivolumab." (PMID 41010985, 2025). "In clinical settings, TLR2 inhibitors are being investigated in combination regimens, enhancing the efficacy of chemotherapy, anti-angiogenic agents (e.g., bevacizumab), and immunotherapies, showing synergy with TLR9 agonists (CpG ODN) in melanoma models." (PMID 41375047, 2025). "Two complementary studies have shown encouraging results combining intratumoral TLR9 (vidutolimob or tilsotolimod) with systemic ICI in melanoma." (PMID 41086813, 2025). "High daily intake of acesulfame (>0.10 mg/kg/day) had a similar trend toward lower ORR and poorer PFS in ICI-treated melanoma and NSCLC, as well as lower MPR and RFS in high-risk resectable melanoma treated with ICI and TLR9 agonist." (PMID 40742298, 2025). "Intratumoral injection of the TLR9 agonist CMP-001 in melanoma patients resulted in partial responses in 46.7% of patients, and a Phase II/III study in melanoma is ongoing." (PMID 41417432, 2025). "Recent clinical studies have explored the anti-melanoma potential of treatments involving TLR-9 agonists." (PMID 39202970, 2024). "Pioneering studies by others have demonstrated CpG as an immunostimulatory molecule that activates innate immunity and induces systemic immune response through TLR9 in solid and blood cancer, including B cell lymphoma and melanoma." (PMID 39618825, 2024). "The TLR9 agonist ODN1826 suppressed tumor burden in a B16-F10 melanoma mouse model, and the most efficient treatment was the locally injected combination of the CpG oligonucleotide TLR9 agonist ODN1826 combined with systemic CTLA-4 blockade." (PMID 39516356, 2024). "Because of the potential for TLR-9 to trigger anticancer responses, its agonists are being increasingly tested in the clinic for melanoma and various other types of cancer." (PMID 39202970, 2024). "CMP-001, a TLR9 agonist, is injected intratumorally into melanoma patients (NCT03618641, phase 2), and the results revealed that 46.7% (14/30) of patients achieved a partial response." (PMID 39516356, 2024). "PF-3512676, one of the earlier synthetic TLR9 agonists to treat melanoma patients, increases pDC and mDC frequency, along with the release of inflammatory cytokines, while markedly reducing Treg cell population in the sentinel lymph nodes (SLN)." (PMID 37936697, 2023). "Tilsotolimod (IMO 2125) is a synthetic TLR-9 agonist studied in intratumor injection in combination with systemic ipilimumab in advanced melanoma refractory to PD-1 inhibitors." (PMID 36831449, 2023). "Given the potential of TLR-9 activation to trigger an anti-tumor immune response, TLR-9 agonists have been trialed as therapeutics for a wide range of malignancies, including melanoma, basal cell carcinoma, lymphoma, and renal cell carcinoma." (PMID 36831449, 2023). "Toll-like receptor-9 (TLR9), which is a target produced from plasmacytoid dendritic cell (pDC) precursors, has lately acquired popularity in melanoma clinical trials." (PMID 37803407, 2023).
melanoma (continued). "Intra-tumoral administration of the TLR9 agonist CpG-B into the skin of early-stage melanoma patients showed improved APC activation and recruitment of cDC1 and CD14+ APC to the injection site and draining lymph nodes." (PMID 37112730, 2023). "MNs were synthesized out of crosslinked hyaluronic acid (HA) and loaded with a model immunomodulatory nanoparticle-containing drug, CpG oligodinucleotides (TLR9 agonist), for cancer therapy in melanoma and colon cancer models." (PMID 36593949, 2023). "In another study, cell membrane vesicles from melanoma cells were combined with CpG oligonucleotides, TLR-9 agonist and DCs-targeting aptamer, enabling specific activation of immune system against cancer, together with a long-term immune memory effect." (PMID 36761725, 2023). "Although TLR-9 is present in melanoma cells of clinical biopsies and also in in vitro cultured melanoma cells including A375 cells, experiments using chloroquine, a compound known to interfere with TLR-9 and its ligand, do not reverse PD-L1/2 downregulation." (PMID 36230620, 2022). "A recent study found that LTF deficiency enhanced lung metastasis of melanoma in an LTF KO mouse model, which was related to the enhancing of the TLR9 pathway." (PMID 35096061, 2022). "In fact, it has been shown in stage I/III melanoma patients that the local administration of CpG-B (also called CpG 7909; PF-3512676), a TLR9 agonist, enhanced the activation state of pDCs and melanoma-specific CTLs responses and reduced Treg frequencies." (PMID 36232698, 2022). "A phase 1b study suggested that intratumorally applied TLR-9 agonist, sd-101 (Dynavax), improved melanoma therapy in combination with pembrolizumab." (PMID 36230620, 2022). "In a phase Ib trial, the type A CpG TLR-9 agonist vidutolimod (CMP‐001) plus pembrolizumab resulted in durable responses in 25% in patients with melanoma refractory to PD‐1 inhibition." (PMID 35449104, 2022). "Secretion of IFNγ and IL-12 and other inflammatory cytokines via TLR7/8 stimulation enabled NK cells to kill HNSCC and melanoma B16 tumor cells while TLR9 triggered cytotoxic activity of these cells on melanoma cells." (PMID 34124272, 2021). "They demonstrated that this novel developed system can encapsulate the melanoma antigen peptide Trp2 and Toll-like receptor-9 (TLR-9) agonist CpG ODN." (PMID 33668746, 2021). "Promising data with TLR9 agonist CMP001 in melanoma has led to the exploration of this agent plus pembrolizumab also in the frontline R/M HNSCC setting (NCT04633278)." (PMID 34540672, 2021). "Similar enhancement in the immune response was obtained by combining the agonists of TLR9 (ODN1826 or MGN1703) with CTLA-4 or PD-1 blockade in a mouse model of poorly immunogenic melanoma." (PMID 34124272, 2021). "A phase Ib trial evaluated intratumoral SD-101, a synthetic CpG oligonucleotide that stimulates Toll-like receptor 9 (TLR9), in combination with pembrolizumab in patients with unresectable or metastatic malignant melanoma." (PMID 32528284, 2020). "A clinical study of IMO-212 (Tilsotolimod), another TLR9 agonist, was conducted in a cohort of 26 patients with PD-1-inhibitor– refractory advanced melanoma." (PMID 32547560, 2020). "Recent studies have revealed that TLR9 agonists can warm “cold” melanoma tumors and reverse ICB resistance by expanding functional T cells, even though TLR9 agonists have been reported to induce immunosuppression 28-30." (PMID 32483468, 2020). "Combination therapy using TLR9 agonists and different immune checkpoint inhibitor are under clinical investigation for treating melanoma and other types of tumors." (PMID 32547560, 2020). "This was currently shown by PTO-modified TLR9 agonists in mouse tumor models and also in a clinical trial in advanced melanoma." (PMID 30621769, 2019).
melanoma (continued). "The phase I trial of tremelimumab plus subcutaneous administration of TLR9 agonist (CPG 7909) in stage IV melanoma or other advanced solid tumors demonstrated durable (>170 days) partial responses in 12% (2/17) of the patients with good tolerability." (PMID 31680963, 2019). "Here we show that intra-tumoral administration of the TLR9 agonist ODN1826 synergizes with CTLA-4 blockade to promote rejection of bi-laterally implanted B16-Ovalbumin (B16-Ova) melanoma." (PMID 31771649, 2019). "A TLR9 agonist of the CpG-ODN B type is being evaluated in clinical trials in patients with melanoma and lymphoma." (PMID 25971982, 2015). "The role of the TLR9 pathway in anticancer treatment has been considered in animal models and patients with renal carcinoma, malignant melanoma, and non-Hodgkin’s lymphoma." (PMID 22714906, 2012). "TLR9 agonists, CpG ODNs, have been combined with RT in various preclinical tumor models, such as, lung, melanoma and fibrosarcoma." (PMID 22666458, 2012). "Beyond melanoma, TLR9 agonist-ICI combinations are advancing in other cancers." (PMID 41086813, 2025). "In melanoma, renal cell cancer and colon cancer, TLR9 ligation has been shown to be protective." (PMID 37112730, 2023). "Vidutolimod (CMP-001) is a TLR-9 agonist packaged within a virus-like particle that has been studied in combination with pembrolizumab as neoadjuvant therapy for fully resected stage III melanoma and advanced melanoma." (PMID 36831449, 2023). "In human melanoma cell lines resistant to anti-PD-1 therapy due to JAK1/2 knock-out mutations, administration of the intratumoral TLR-9 agonist SD101 with anti-PD-1 overcame this resistance by the activation of IFN signalling and the stimulation of natural killer (NK) cells." (PMID 35449104, 2022). "A trial that evaluated the efficacy of TLR9 agonist SD-101 combined with the PD-1 antibody pembrolizumab for the treatment of patients with advanced melanoma reported an overall ORR of 78%, estimated 12-month PFS of 88%, OS of 89%, and tolerability of a good level." (PMID 35833121, 2022). "In addition, it was demonstrated that JAK1/JAK2 mutation in melanoma patients, which provokes resistance to anti-PD1 mAb treatment, can be overcome with the treatment of SD-101 TLR9 agonist." (PMID 36672572, 2022). "In a previous study, we found that the combination of the Toll-like receptors 9 (TLR9) agonist CpG oligodeoxynucleotides 1826 (CpG 1826) and M-M inhibited the growth of melanoma B16-MUC1 cells subcutaneously transplanted into mice and mediated MUC1-specific humoral and cellular immune responses." (PMID 36142800, 2022). "Hence, it will be interesting to investigate the TLR9 activation in melanocytes in patients with melanoma." (PMID 33510592, 2021). "LTF may play a protective role in melanoma metastasis by inducing differentiation and apoptosis of myeloid-derived suppressor cells (MDSCs) and up-regulating TLR9 expression." (PMID 33585219, 2020). "We sought to test whether activation of TLR9 through intra-tumoral injection in the B16-Ova melanoma model could potentiate systemic, sterilizing anti-tumor immunity in conjunction with blockade of the T cell immune checkpoint receptor CTLA-4." (PMID 31771649, 2019). "Indeed, induction of inflammation in the skin by local injection of a TLR-9 agonist and GM-CSF into the scar of resected melanoma resulted in selectively increased numbers of cDC1 in sentinel lymph nodes." (PMID 30930897, 2019). "The activation of intratumoral pDCs by TLR-9 agonist may induce melanoma regression via natural killer (NK) cell-dependent pathways in a C57BL/6 melanoma model." (PMID 31307548, 2019). "In addition to TLR9 stimulated cytotoxicity of NK cells on B16 melanoma cells, the secretion of inflammatory cytokines as IFNγ and IL-12 was promoted via TLR7/8 activation, which in order aided the NK cells to eliminate the HNSCC cells and B16-F10 melanoma cancer cells." (PMID 37936697, 2023).
melanoma (continued). "Likewise, preliminary data derived from a phase I/II trial with PD-L1-refractory melanoma (ILLUMINATE 301) showed maturation of myeloid type 1 DCs (mDC1s) in response to an intratumorally administered synthetic TLR-9 agonist (IMO-2125, tilsotolimod) in combination with CTLA-4 blocking." (PMID 36230620, 2022). "Recent studies using the melanoma mouse model demonstrated that JAK1/2 knockout resistance could be overcome with anti-PD-1 Ab in combination with the TLR9 agonist, which activates TLR9-type IFN signaling, thereby increasing infiltration of T cells and NK cells in the tumor." (PMID 35432377, 2022). "Moreover, TLR-9 agonists will probably find more applications in the treatment of those neoplasms for whom immune components have a more relevant role in their development and maintenance, such as melanoma." (PMID 28548068, 2014). "Apart from cGAS/STING activation, toll-like receptor 9 (TLR9) and absence in melanoma 2 (AIM2) initiate responses to cytosolic DNA." (PMID 38990864, 2024). "Based on these results, clinical trials evaluating the TLR9 agonist or CD122 preferential IL-2 agonist in combination with anti-PD-1 Ab, for melanoma, are now ongoing." (PMID 35432377, 2022). "Using single-cell RNA-sequencing, we address this by comparing the tumor immune composition of B16F10 melanoma following treatment with agonists of TLR3, TLR7, and TLR9." (PMID 34381732, 2021). "Neoadjuvant intralesional therapy for melanoma has been studied in 2 phase II trials using talimogene laherparepvec (T-VEC) and ‘CheckMate Pharmaceuticals’©, toll-like receptor 9 agonist (CMP-001)." (PMID 33920967, 2021). "Here we treat B16F10 melanoma with agonists of the endosomal TLRs TLR3, TLR7 and TLR9 to understand the influence of these agents on immune polarization in a ‘cold’ tumor model." (PMID 34381732, 2021). "Subcutaneous B16F10 melanoma tumors were grown to 150 mm3 then injected I.T. with selective agonists targeting TLR3, TLR7or TLR9, or vehicle control respectively." (PMID 34381732, 2021). "Using both a TLR9 agonist (MGN1703) and a CTLA-4 antibody (9D9-IgG2a) of increased potency cured 50% of bi-lateral B16-F10 melanoma." (PMID 31771649, 2019). "We also demonstrated that human DCs coincubated with H-1PV-induced melanoma TCLs showed enhanced expression of TLR3, TLR9, and other maturation markers." (PMID 24822170, 2014). "A more recent analysis of combined vs. monotherapy in a mouse melanoma model showed that combined activation via CD40 and TLR9 results in tumor-infiltrating CD8+ T cells at a very high frequency and with potent anti-tumor activity." (PMID 19906293, 2009). "Detection of abnormal nucleic acids in the cytosol is mediated by internal sensors, such as cyclic GMP–AMP synthase (cGAS), Toll-like receptor 9 (TLR9) and absent in melanoma 2 (AIM2) 41,42." (PMID 40768308, 2025). "SD‐101, a CpG‐C TLR9 agonist, had transient single‐agent activity in murine models that has not been confirmed in patients with advanced nonocular melanoma." (PMID 40753466, 2025). "The CpG oligonucleotide TLR9 ODN 1826 agonist has been shown to effectively augment the therapeutic potential of checkpoint blockade through locally delivered ODN 1826 and systemic CTLA4 or PD-1 blockade antibody in the B16 melanoma mouse model." (PMID 39618825, 2024). "Recently, it was reported that the TLR9 agonist PRINT-CpG was effective in promoting tumor regression in mouse models of non-small cell lung cancer, and the TLR7/8 agonist also has an antitumor effect in melanoma, which was consistent with this study." (PMID 37296415, 2023). "Although no TLR-9 agonists currently have received FDA approval for the treatment of melanoma, several clinical trials have demonstrated potential clinical benefit and are undergoing further investigation." (PMID 36831449, 2023).